IRAK1 (interleukin 1 receptor associated kinase 1)
Diseases named in the same sentence as IRAK1 in open-access papers (continued):
Sharing a sentence is not in itself a finding about the gene and the disease.
primary effusion lymphoma (3 papers, 2015 to 2024). A large B-cell lymphoma located in the body cavities, characterized by pleural, peritoneal, and pericardial fluid lymphomatous effusions and that is always associated with human herpes virus-8 (HHV-8). "The IRAK1 mutation has been found in Primary effusion lymphoma (PEL), a disease that develops in HIV-positive patients, in association with viral infections." (PMID 25983693, 2015). "Oncogenic activation of the TLR/IL1R pathway is found in several B-cell lymphomas, often in conjunction with the MYD88 L265P gain of function mutation and 100% of primary effusion lymphoma harbor IRAK1 gain of function mutations leading to constitutive IRAK1 activation." (PMID 26068967, 2015). "A study focused on primary effusion lymphoma (PEL) reported a missense mutation in IRAK1, resulting in a Phe196Ser substitution that renders IRAK1 constitutively active, marking it as the main driver for Kaposi sarcoma herpesvirus lymphoma." (PMID 39451208, 2024).
respiratory infections (3 papers, 2017 to 2023). "Moreover, cases with a duplicated region inclusive of IRAK1 with no history of respiratory infections have been reported, as has a female patient who had recurrent respiratory infections but not a duplicated IRAK1 region." (PMID 35313898, 2022).
Rett syndrome (3 papers, 2007 to 2021). A severe neurodevelopmental disorder affecting the central nervous system. "It was then shown that both miR-146a and miR-146b could downregulate IRAK1 expression in vitro and it was proposed that in Rett syndrome the downregulation of miR-146a/b contributes to the overexpression of IRAK1." (PMID 31019524, 2019).
Splenomegaly (3 papers, 2016 to 2022). Abnormal increased size of the spleen. "Neither ABIN1[D485N] × IRAK4[D329A] mice nor ABIN1[D485N] × IRAK1[D359A] mice developed splenomegaly and, consistent with these observations, the levels of ANAs, dsDNA Abs, and other IgGs and IgM in the serum of these mice were similar to WT mice." (PMID 27807192, 2016). "The combination greatly prolonged the survival of CML mice and reduced the splenomegaly of CML mice, whereas IRAK1/4 inhibitor alone did not." (PMID 35022428, 2022).
Stroke (3 papers, 2013 to 2025). Sudden impairment of blood flow to a part of the brain due to occlusion or rupture of an artery to the brain. "Its expression is elevated in peripheral blood mononuclear cells and the brain white-matter lesions of MS patients, and it enhances oligodendrogenesis by targeting IRAK-1 in a rat stroke model." (PMID 40234289, 2025). "The authors thought that the therapy with VELCADE and tPA abolished the inactivation of fibrin/fibrinogen on NF-κB by directly inhibiting stroke-activated TLR2, TLR4, and IRAK1 and suppressing inflammatory respond." (PMID 23864765, 2013).
thyroid cancer (3 papers, 2022 to 2023). "In addition, a study of thyroid cancer samples from The Cancer Genome Atlas (TCGA) revealed that miR-146b-5p-mediated regulation of the interleukin-1 receptor-associated kinase 1 gene (IRAK1) distinguishes the conventional PTC form." (PMID 37547301, 2023). "IRAK1 expression was upregulated in almost all tumors but thyroid carcinoma (THCA)." (PMID 35211171, 2022). "In contrast, there was only one cancer type, thyroid carcinoma (THCA), which showed lower expression of IRAK1 in tumor tissues." (PMID 36421353, 2022).
Type 2 diabetes (3 papers, 2019 to 2022). "Moreover, microRNA‐146a downregulation is associated with neuron apoptosis by the elevation of the protein levels of IRAK1 and TRAF6 in peripheral neuropathy and cultured dorsal root ganglia neurons in the mouse model of type 2 diabetes." (PMID 30599464, 2019).
B-cell lymphomas (2 papers, 2015 to 2024). "The covalent IRAK1 inhibitor JH-X-119-01 shows promise in B-cell lymphomas, emphasizing the significance of covalent bonds in its activity." (PMID 38792088, 2024).
diabetic nephropathy (2 papers, 2022 to 2024). "In a mouse model of diabetic nephropathy, downregulation of IRAK1 could inhibit kidney damage in mice by inhibiting the apoptosis of podocytes and thereby reducing proteinuria." (PMID 36091017, 2022).
emphysema (2 papers, 2021 to 2023). "In particular, upregulation of MMP-1 expression can be involved in the progression of emphysema by regulating the MyD88/IRAK1 signalling pathway." (PMID 35388750, 2023). "CS-related TLR4 signaling was shown to increase MMP-1, a crucial actor in emphysema, in a MyD88- and IRAK1-dependent manner, while CS-exposed TLR4–/– mice were protected from emphysema, impaired lung function, airway fibrosis, and collagen deposition in small airways as compared with wild-type mice." (PMID 34248677, 2021).
endothelial dysfunction (2 papers, 2017 to 2022). In vascular diseases, endothelial dysfunction is a systemic pathological state of the endothelium (the inner lining of blood vessels) and can be broadly defined as an imbalance between vasodilating and vasoconstricting substances produced by (or acting on) the endothelium. "This demonstrates that miR-146a-5p may have therapeutic potential, mitigating endothelial dysfunction through the downregulation of both IRAK-1 and ICAM-1." (PMID 28824448, 2017).
epilepsy (2 papers, 2015 to 2022). A brain disorder characterized by episodes of abnormally increased neuronal discharge resulting in transient episodes of sensory or motor neurological dysfunction, or psychic dysfunction. "Therefore, IRAK1 plays an essential role in the onset of epilepsy." (PMID 34969353, 2022). "Our results showed that IRAK1 (P = 1.04 × 10−7), the targets of miR-146a, MAPKBP1 (P = 10.44 × 10−7) and CASP6 (P = 0.001), targets of miR-106b, were down-regulated, whereas MAP2K6 (P = 5.30 × 10−5), target of miR-194-5p, was up-regulated in epilepsy patients compared with normal controls." (PMID 25825351, 2015).
head and neck squamous cell carcinoma (2 papers, 2020 to 2024). A squamous cell carcinoma that arises from any of the following anatomic sites: lip and oral cavity, nasal cavity, paranasal sinuses, pharynx, larynx, and salivary glands. "Sixty two genes potentially trans-regulated by the lncRNAs such as CD44 (Hyaluronan/CD44 signaling plays an important role in head and neck squamous cell carcinoma progression) and interleukin 1 receptor associated kinase 1 (IRAK1) are involved in the EBV infection pathway." (PMID 32272952, 2020).
influenza (2 papers, 2013 to 2022). An acute viral infection of the respiratory tract, occurring in isolated cases, in epidemics, or in pandemics; it is caused by serologically different strains of viruses (influenzaviruses) designated A, B, and C, has a 3-day incubation period, and usually lasts for 3 to 10 days. "Our study thus exemplifies how our network analysis can identify potential regulators of influenza pathogenicity for experimental testing, for example, by assessing influenza virus infections in IRAK1-deficient cells or mice." (PMID 23300433, 2013). "The protein IGFALS, which distinguishes severity of WNV infection, facilitates ubiquitination of signaling mediators IRAK1 and TRAF6 to inhibit influenza viral replication and has recently been shown to be a sensitive biomarker of COVID-19 infection." (PMID 36569838, 2022).
ischemia (2 papers, 2012 to 2014). A hypoperfusion of the BLOOD through an organ or tissue caused by a PATHOLOGIC CONSTRICTION or obstruction of its BLOOD VESSELS, or an absence of BLOOD CIRCULATION. "The findings of the present study demonstrate that enhanced levels of the Irak1 protein at the intestinal epithelium following ischemia contribute to the Tlr-mediated tissue damage associated with I/R injury." (PMID 23143987, 2012). "Thus, we selected 60 min of ischemia and 8 h of reperfusion as a point to evaluate the relationship between miR-146a and key kinases in the TLR signaling pathway, IRAK1 and TRAF6, in the murine liver during I/R injury." (PMID 24987958, 2014).
Kaposi's sarcoma (2 papers, 2019 to 2023). A malignant neoplasm characterized by a vascular proliferation which usually contains blunt endothelial cells. "miRNA-K5 and miRNA-K9 associated with Kaposi's sarcoma target myeloid differentiation primary response gene-88 (MyD88) and Interleukin 1 receptor-associated kinase 1 (IRAK1), which further reduces the expression of inflammatory cytokine and clearance by the immune system." (PMID 32038627, 2019). "IRAK1 has also been proposed to play an oncogenic role in Kaposi sarcoma." (PMID 37370720, 2023).
Liver fibrosis (2 papers, 2016 to 2018). "Liver fibrosis along with inflammatory changes observed in ABIN1[D485N] mice were drastically reduced after crossing to IRAK4[D329A] or IRAK1[D359A] mice but were not reduced by crossing to IFNAR1-KO mice." (PMID 27807192, 2016).
low grade glioma (2 papers, 2022 to 2023). A grade I or grade II glioma arising from the central nervous system. "Evidence from both in vitro and in vivo studies shows that the highest expressed form of IRAK1 in low-grade gliomas (LGG) inhibits cell apoptosis and increases malignancy." (PMID 37370767, 2023). "The findings of this study highlight the crucial role of the oncogenic gene IRAK1 in low-grade glioma (LGG)." (PMID 35211171, 2022).
memory impairment (2 papers, 2019 to 2021). "MiR-146a restored learning and memory impairment in an experimental mouse model of Postoperative cognitive dysfunction (POCD) by targeting interleukin-1 receptor-associated kinase 1 (IRAK1) and TNF-receptor-associated factor 6 (TRAF6)." (PMID 31133802, 2019).
myocardial inflammation (2 papers, 2022 to 2023). "However, miR-192-5p could effectively rescue mice from coxsackievirus B3 (CVB3)-induced viral lethal myocarditis through switching myocardial-infiltrating macrophages to a predominant M2 phenotype by targeting interleukin-1 receptor-associated kinase 1 (IRAK1)." (PMID 37138859, 2023). "Excessive activation of TLR4/IRAK1/TRAF6/NF-κB pathway commonly exists in myocardial inflammation." (PMID 36148071, 2022).
Other metabolic disease (2 papers, 2018 to 2022). "MiR-146a, which affects IRAK1 and TRAF6, has been extensively employed to investigate the role of IRAK1 in metabolic diseases." (PMID 30279971, 2018).
Peri-Implantitis (2 papers, 2017 to 2021). An inflammatory process with loss of supporting bone in the tissues surrounding functioning DENTAL IMPLANTS. "Our data showed that the levels of TLR2, TLR4, IRAK1, and TRAF6 gene expression were in agreement with that in bone loss, suggesting peri-implantitis augmented by glycemic fluctuation were at least partly mediated through the activation of TLR2/4 signaling." (PMID 34401982, 2021). "Thus, down-regulation of miR-146a in peri-implantitis should diminish the inhibition of IRAK1 and TRAF6 and promote activation of the NF-κB and MAPK pathways." (PMID 28864780, 2017).
renal fibrosis (2 papers, 2022 to 2025). A final common manifestation of a wide variety of chronic kidney diseases characterized by glomerulosclerosis and tubulointerstitial fibrosis. "Inhibits EMT and inflammation, reducing renal fibrosis by targeting TRAF6 and IRAK1." (PMID 40895189, 2025).
systemic sclerosis (2 papers, 2017 to 2024). A chronic disorder, possibly autoimmune, marked by excessive production of collagen which results in hardening and thickening of body tissues. "Yet, according to findings from a comprehensive European study, an IRAK1 haplotype containing the functional variant 196Phe (rs1059702), situated on Xq28, was identified as conferring susceptibility to systemic sclerosis (SSc)." (PMID 38790215, 2024).
ZIKV infection (2 papers, 2018 to 2020). "IRAK1 excepted, these proteins have been previously identified as upregulated during ZIKV infection." (PMID 32817655, 2020).
abortion (1 paper, 2021). the ending of pregnancy by removing a fetus or embryo before it can survive outside the uterus. "Expression of IRAK1 mRNA is increased in the deciduae of patients with unexplained recurrent spontaneous abortion compared with that in healthy women, which is the cause of the immune intolerance of fetal-placental unit." (PMID 34394755, 2021).
acute graft versus host disease (1 paper, 2024). A syndrome of immunologically mediated tissue damage that may occur following an allogeneic transplant, usually affecting the skin, liver, and GI tract. "IRAK1 controls the activation of antigen-presenting cells (APCs) under inflammatory conditions, and suppressing IRAK1 may potentially reduce APC activation and alleviate acute graft-versus-host disease (aGVHD)." (PMID 38792088, 2024).
acute monocytic leukemia (1 paper, 2024). Acute monoblastic leukemia (AML-M5), is one of the most common subtypes of acute myeloid leukemia (AML) that is either comprised of more than 80% of monoblasts (AML-M5a) or 30-80% monoblasts with (pro)monocytic differentiation (AML-M5b). "Apoptosis analysis in the IRAK1/4 dual inhibitor-treated murine monocyte/macrophage leukemia cell line RAW 264.7 and human acute monocytic leukemia cell line THP-1 showed higher induction of apoptosis compared to when treated with the IRAK1 selective inhibitor JH-X-119-01." (PMID 38792088, 2024).
acute respiratory distress syndrome (1 paper, 2022). Progressive and life-threatening pulmonary distress in the absence of an underlying pulmonary condition, usually following major trauma or surgery. "The alternative splicing of MyD88 and IRAK1 has been examined in a cohort of patients with Acute Respiratory Distress Syndrome (ARDS)." (PMID 36531997, 2022).
age-related macular degeneration (1 paper, 2013). Age-related loss of vision in the central portion of the retina (macula), secondary to retinal degeneration. "These two microRNAs could play a role in inflammatory processes underlying age-related macular degeneration or other retinal degenerative diseases through their ability to negatively regulate the nuclear factor-κB pathway by targeting the expression of IRAK1." (PMID 23592910, 2013).
AIDS (1 paper, 2022). A syndrome resulting from the acquired deficiency of cellular immunity caused by the human immunodeficiency virus (HIV). "We found that all of 3 IRAK isoforms (IRAK1, IRAK2, and IRAK4) we tested were highly expressed in AIDS-KS tissues when compared to those in normal skin tissues." (PMID 36457850, 2022).
aortic valve stenosis (1 paper, 2019). Aortic valve stenosis (AVS) is a condition characterized by narrowing of the heart's aortic valve opening. "In the present study, we have investigated the expression of miR-146a and its targets, TLR4 a IRAK1, in aortic valve stenosis." (PMID 31294031, 2019). "This study investigated the expression of miR-146a and of its targets, TLR4 and IRAK1, in valvular tissue obtained from the patients with aortic valve stenosis." (PMID 31294031, 2019).
atrial fibrillation (1 paper, 2022). A disorder characterized by an electrocardiographic finding of a supraventricular arrhythmia characterized by the replacement of consistent P waves by rapid oscillations or fibrillatory waves that vary in size, shape and timing and are accompanied by an irregular ventricular response. "SGLT-2i dapagliflozin may prevent diabetic rats' atrial remodeling and reduce the inducibility of atrial fibrillation partly by targeting TLR4/IRAK1/TRAF6/NF-κB inflammatory pathway." (PMID 36148071, 2022). "TLR4/IRAK1/TRAF6/NF-κB, collagen I proteins expressions and incidence of atrial fibrillation (27.3%) were increased in DM group." (PMID 36148071, 2022). "Finally, in order to reveal the possible mechanism, we verified the role of TLR4/IRAK1/TRAF6/NF-κB in the inhibition of atrial remodeling and atrial fibrillation by DAPA." (PMID 36148071, 2022).
avian influenza (1 paper, 2020). Infection of domestic and wild fowl and other birds with influenza A virus. "Infected with CK/TX/02/H5N3 avian influenza, reductive miR-146b enhanced the expression of IL-1 receptor associated kinase 1 (IRAK1) and TNF receptor-associated factor 6 (TRAF6)." (PMID 32957919, 2020).
bacterial meningitis (1 paper, 2022). Inflammation of the membranes surrounding the brain and spinal cord due to a bacterial infection. "In summary, our study uncovers the involvement of lncC11orf54-1 in IRAK1–NF-κB signaling, and it functions as a positive regulator of inflammatory responses in meningitic E. coli-induced neuroinflammation, which may be a valuable therapeutic and diagnostic target for bacterial meningitis." (PMID 34980188, 2022).
Behcet's syndrome (1 paper, 2020). "An increased expression of IRAK1 is associated with Behcet's syndrome, which is characterized by multiple inflammation in the body (Sun, Yang, Yang, & Ye, 2018)." (PMID 31605433, 2020).
celiac disease (1 paper, 2015). An autoimmune genetic disorder with an unknown pattern of inheritance that primarily affects the digestive tract. "Although allele and genotype frequencies of IRAK1 and SH2B3 were insignificantly different between patients and controls, a potential synergistic effect was seen between MMEL1 and SH2B3 genes, reinforcing the significance of MMEL1 in celiac disease susceptibility." (PMID 26843707, 2015).
cholera (1 paper, 2017). "The expression of IRAK1 and TRAF6 was only down-regulated in 2 and 3 out of 6 cholera patients at the acute stage of disease although miR-146a and miR-155 were expressed at high levels." (PMID 28319200, 2017).
cholesteatoma (1 paper, 2015). A pathologic process characterized by the proliferation of keratinizing squamous epithelium resulting in the accumulation of keratin and cells in the middle ear and/or mastoid. "Indeed, we found a significantly robust upregulation of the proinflammatory-related genes TNFα, IL1β, IRAK1, p65, NOD2, and a downregulation of IKK2 in cholesteatoma." (PMID 25922834, 2015).
chorioamnionitis (1 paper, 2025). A morphologic finding indicating inflammation of the fetal sac membranes. "In addition, p-IRAK1 protein expression is upregulated in fetal membranes from females delivering preterm compared to no-chorioamnionitis controls, suggesting that IRAKI is involved in inflammation-induced preterm birth." (PMID 40218311, 2025).
Cirrhosis (1 paper, 2021). A chronic disorder of the liver in which liver tissue becomes scarred and is partially replaced by regenerative nodules and fibrotic tissue resulting in loss of liver function. "Patients with decompensated cirrhosis presented a more limited alteration in TLR signalling genes, including 6 of the 17 upregulated genes observed in compensated cirrhosis, SIGIRR, IRAK1, HSPA1A, TOLLIP and ELK1, as well as downregulation of IL-1B." (PMID 34774066, 2021).
cognitive decline (1 paper, 2025). "As to POCD, miR-146a is reported to be associated with cognitive decline by suppressing hippocampal neuroinflammation in mice, via regulation of the IRAK1/TRAF6/NF-κB pathway." (PMID 40718798, 2025).
depression (1 paper, 2021). "Our results showed that the expression levels of TLR4, MyD88, NF-κB-p65, TAK1, IRAK1, TRAF6, inflammasome-related NLRP3, ASC, and caspase-1 were all increased in rats of the depression model group." (PMID 33505499, 2021).
ductal carcinomas (1 paper, 2007). "Majority of genes with this function were upregulated in ductal carcinomas such as AHCTF1, IRAK1, NRIP1, ADNP." (PMID 17389037, 2007).